KRAS (KRas proto-oncogene, GTPase)
Diseases named in the same sentence as KRAS in open-access papers (continued):
Sharing a sentence is not in itself a finding about the gene and the disease.
tumor (continued). "The median OS in the group of patients with wt-KRAS and wt-BRAF tumours was 107.4 months (95% CI: 82- 132.9 months) and in the group of patients with wt-KRAS and mt-BRAF tumours 44.9 months (95% CI: 28.4- 61.5 months)." (PMID 22933967, 2011). "Moreover, because we concurrently assessed clinical, pathologic and tumor molecular variables such as the CpG island methylator phenotype (CIMP), LINE-1 methylation, KRAS, BRAF and PIK3CA mutations, we could evaluate the effect of TGFBR2 or BAX mutation independent of these potential confounders." (PMID 21949851, 2011). "A highly unfavourable outcome in patients with KRAS and BRAF wild-type tumours with overexpression of TOPK was noted (P=0.018)." (PMID 19935791, 2010). "A total of 394 tumor samples – 198 from the cetuximab group and 196 from the BSC group – were available for KRAS analysis, accounting for 68.9% of the original study population." (PMID 20680106, 2010). "More recently, the analysis of KRAS, BRAF and PIK3CA in tumour invasion fronts, lymph nodes and distant metastases revealed a discordance between primary tumours and lymph node metastases of 31, 4 and 13%, respectively." (PMID 21139621, 2010). "We examined the paired tumor and normal tissue specimens of 86 CRC patients for the occurrence of aberrations in MCR region of SMAD4 and exon 1 of KRAS by PCR-SSCP and/or PCR-Direct sequencing." (PMID 20565773, 2010). "Diffuse TOPK expression was observed in 19 (82.6%) KRAS wild-type and 21 (91.3%) BRAF wild-type tumours." (PMID 19935791, 2010). "Hence, patients with mutant KRAS tumors are not eligible for treatment with these drugs; the clinician must have the information on KRAS mutation status of the tumor when assessing the patient; the information provided for clinical decision making must be accurate." (PMID 19888477, 2009). "Examples are 'PI3K/AKT', 'KRAS', 'PTEN', 'WNT-beta catenin' and 'MAPK signaling' pathways, as well as a group of genes specific of human tumor initiating cells (CD44+CD24-)." (PMID 19327144, 2009). "A first group found no KRAS mutations in tumors from 11 cetuximab-responding patients, whereas 13 of the 19 nonresponders (p = 0.0003) had a KRAS-mutated tumor, leading the authors to suggest that KRAS mutational status could serve to exclude cetuximab use in mCRC." (PMID 18544172, 2008). "Therefore, it is not known whether the activation of KRAS or BRAF mutations alters the effects of these pathways on tumour progression." (PMID 19018267, 2008). "Comparison of KRAS mutant-selective transcription and signaling in murine and human PDAC cell lines, GEMMs, and patient-derived xenograft (PDX) mouse models revealed that direct KRAS-mediated PI3K activation is necessary for robust tumor initiation in GEMMs." (PMID 41556816, 2026). "It outlines the stringent technical requirements and testing methods necessary to ensure high fidelity to the original tumor tissue, including morphological assessment, pathological biomarker expression (e.g., CK19, CK7), and genetic concordance (e.g., NRG1, KRAS)." (PMID 42026891, 2026). "This suggests that in KRAS-mutant PDAC, tumor progression and stromal formation may be further promoted by FGF19 through its synergistic action with HMGA1." (PMID 41328353, 2026). "Interestingly, statins, widely used to lower cholesterol, have shown selective efficacy in killing KRAS mutant (KRASMUT) cells in vitro and in tumor models." (PMID 41511990, 2026). "KRAS-driven tumors also show broader metabolic and signaling changes (including dysregulated glucose/glutamine/fatty acid metabolism and activation of MAPK and HIF-1-related cascades) that support tumor growth and indirectly reinforce immune escape." (PMID 41596586, 2026).
tumor (continued). "Increasing evidence indicates that oncogenic drivers, including EGFR, ALK, KRAS, MET, RET, and BRAF, actively shape the tumor immune microenvironment (TIME) by regulating antigen presentation, immune cell infiltration, cytokine signaling, metabolic programs, and immune checkpoint expression." (PMID 42079655, 2026). "Here, we highlight the complex interplay between KRAS signaling, the transcriptional coactivator YAP and SFKs in the development of PDAC, including the importance of these signaling proteins in metabolic reprogramming and in shaping the tumor microenvironment." (PMID 41484057, 2026). "In humans, subtypes of the Let-7 family (a-g and i) share a high degree of sequence similarity and are primarily known as tumor suppressors that downregulate the expression of target genes such as MYC, KRAS, and LIN-28 effecting cell differentiation, growth and survival." (PMID 41510819, 2026). "In addition, some genes including ABCG1, KRAS, MMP2, MMP9 were inhibited by cyAV3.3 in homospheroids, which indicates the direct effect of ITGA5 inhibition on resistance in tumor cells." (PMID 41584360, 2026). "Using the ID8 murine OC cell line transduced with c-MYC or KRAS, researchers found that both oncogenes markedly accelerated tumor progression in vivo, despite no increased proliferation in vitro." (PMID 41020848, 2025). "Since KRAS is a well-recognized oncogene in the NSCLC, its inhibition could potentially reduce tumor progression." (PMID 39895781, 2025). "HRS-4642 is another selective and non-covalent KRAS G12D inhibitor exhibiting anti-tumor efficacy confirmed in preclinical studies, which also synergizes with proteasome inhibitors." (PMID 40597785, 2025). "Conversely, when oncogenic KRAS signaling is accompanied by genetic inactivation of CIC, the complete lack of CIC-mediated repression would allow tumor initiation without KRAS allelic imbalances." (PMID 41219537, 2025). "Conversely, activation of EGFR/KRAS pathways may suppress PTTG gene expression, thereby modulating cell cycle dynamics and limiting tumor progression." (PMID 40877987, 2025). "Clinically, the presence of KRAS or BRAF mutations on ICI response has not been fully established and varies across tumour types." (PMID 40362630, 2025). "Combination with MEK inhibitors enhances the inhibitory effect on KRAS-mutant tumors, while co-administration with YAP inhibitors synergistically inhibits tumor metastasis; in tumors with abnormal activation of the PI3K/AKT pathway, RASSF4 overexpression enhances the efficacy of PI3K inhibitors." (PMID 41007433, 2025). "Recently, preclinical studies on TSN1611, a potential KRAS G12D(ON/OFF) inhibitor developed by Tyligand Bioscience, showed its favorable safety profiles and significant in vitro and in vivo anti-tumor activity in various KRAS G12D-mutant models, as well as its brain penetration potential." (PMID 40597785, 2025). "Biomarkers such as tumor-infiltrating lymphocytes in the tumor immune microenvironment (TIME), programmed death-1 ligand (PD-L1) expression, KRAS alteration, and TGFBR2 may predict the efficacy of pharmacotherapy including ICIs for biliary tract cancer." (PMID 40647383, 2025). "Signaling pathways that drive tumor progression and therapy resistance include KRAS, TGF-β, Notch, hypoxia-inducible factor (HIF), and Wnt/β-catenin." (PMID 40230862, 2025). "Currently, because KRAS-mutant lung adenocarcinoma (LUAD) is resistant to the MEK inhibitor trametinib, it has been found that trametinib in combination with ICIs for the treatment of LUAD exerts a synergistic anti-tumor effect." (PMID 40557151, 2025).
tumor (continued). "Notably, in KRAS G12C-mutant NSCLC models, GDC-6036 combined with GDC-1971 reduced tumor growth more effectively than either drug alone and was well-tolerated." (PMID 40303413, 2025). "Of note, the only RASGRF fusion we identified in a PDAC with a concurrent KRAS mutation is MSH3-RASGRF2 (which lacks the PH1 but not DH domain), suggesting the fusion is unlikely to be an oncogenic driver in that tumor." (PMID 40615519, 2025). "Its upregulation is strongly associated with aggressive tumor features (VI, PNI, advanced stage, low differentiation) and molecular alterations (pMMR status, MLH1-deficient, KRAS mutations, HER-2 positive, PD-L1 CPS negative, and high KI-67 expression)." (PMID 41100061, 2025). "It has been show that in KRAS-mutant PDAC, spleen tyrosine kinase (Syk) and tripartite motif containing 21 (TRIM21) accelerate tumor progression toward malignancy by regulating the ubiquitination of BCAT2 to maintain the catabolism and mitochondrial respiration of BCAAs90." (PMID 41281760, 2025). "Similarly, in the KRAS G12C-mutant CT26 syngeneic mouse model, although MRTX849 monotherapy significantly inhibited tumor growth and induced partial tumor regression, combination therapy with an anti-PD-1 antibody dramatically enhanced therapeutic efficacy." (PMID 40303413, 2025). "Importantly, the combination of KRAS ASO and immRNA delivered by RBCEVs induced synergistic activation of RIG-I, leading to robust induction of tumor cell death and upregulation of IFNs in KRAS-dependent cancers both in vitro and in vivo." (PMID 40585984, 2025). "KRAS and BRAF mutations were determined by regular diagnostics for all patients, with half determined on metastatic tissue and the other half on primary tumor tissue, not necessarily from the same lesion as the PDO biopsy." (PMID 40982295, 2025). "Currently, KRAS allelic imbalances are not taken into consideration for the design of therapeutic strategies, even though they alter tumor biology." (PMID 40227826, 2025). "Using the KRAS-G12D inhibitor MRTX1133 reduced glycolysis and tumor weight in vivo." (PMID 39883522, 2025). "Sequencing of the tumor revealed the lack of EGFR, KRAS or ALK mutations, rendering the patient ineligible for targeted therapy options." (PMID 41146188, 2025). "In APC; KRAS mut mice, DSS significantly increased tumor number and size in the proximal colon." (PMID 41285904, 2025). "As KRAS WT amplification is most frequently observed in gastric, esophageal, and gastroesophageal junction cancers, we subsequently selected CDX and PDX models from these tumor types." (PMID 39711431, 2025). "In addition, combination therapy involving the depletion of extracellular asparagine (e.g., ASNase) and AKT inhibition decreased tumor growth, suggesting that ASNS can be a promising therapeutic target for KRAS-driven NSCLC." (PMID 39796613, 2025). "Stronger anticancer effect in animals with KRAS and BRAF mutant by decreasing intracellular glucose and energy production due to intracellular ROS accumulation and GAPDH inhibition compared wild type tumor (P < 0.05)." (PMID 40950984, 2025). "The cftDNA content in plasma is quite low (rarely higher than 1% of total cfDNA), and it is not expected to enable the detection of KRAS CNG at the same frequency as it would in a tumor tissue sample." (PMID 41009333, 2025). "This suggests that TRPM7 kinase deletion has no impact on KRAS G12C tumor progression nor metastasis dissemination." (PMID 40274768, 2025). "MEK inhibitors have been previously evaluated in the context of PDAC and exert little tumor control as monotherapies in mouse models thereof and, in KRAS mutant settings, are primarily cytostatic rather than cytotoxic." (PMID 40299790, 2025). "MC-38 harbors a KRAS mutant and MSI/MMR-d and is a cell line model of an immune hot tumor." (PMID 40013140, 2025). "The tumor tissue dimensions of the knockdown‐KRAS‐SMMC‐7721 xenograft model have no changes after treatment of NSC48160." (PMID 40390765, 2025).
tumor (continued). "For example, KRAS and TERT exhibited strong positive correlations with immune cell types, including CD8 T, iTreg, and Tr1 cells, suggesting their involvement in the immune response within the tumor microenvironment." (PMID 40450370, 2025). "Further experiments confirmed that inhibiting ASNS or combining L-asparaginase with rapamycin significantly blocks KRAS-mutant tumor proliferation, indicating ASNS-driven asparagine synthesis is key to metabolic adaptation and therapy resistance in KRAS-mutant CRC." (PMID 41020873, 2025). "Tumor shrinkage was observed in the vast majority (82%) of the LGSOC patients regardless of KRAS status." (PMID 41009492, 2025). "Restoring SLC25A21 expression reduced KRAS signaling and sensitized CRC tumours to cetuximab, suggesting that targeting SLC25A21 could enhance therapeutic efficacy." (PMID 41154605, 2025). "Tumor cells of the C0 group enriched in TGF-β signaling and angiogenesis, G2M checkpoint, tumor cells of the C2 group enriched in hedgehog signaling, KRAS signaling, and G2M checkpoint, tumor cells of the C3 group enriched in epithelial-mesenchymal transition (EMT)." (PMID 39895784, 2025). "Second, resistance of KRAS-directed drugs remains evitable, with tumor cell-autonomous as well as non-autonomous (for example, related to TME) mechanisms, which can be further categorized as primary or acquired resistance." (PMID 40885393, 2025). "KRAS-induced high calcium and integrin-binding protein 1 (CIB1) expression also alters the metabolic profile, leading to increased glycolysis metabolism, oxidative phosphorylation, and hypoxia pathway activation, which promotes tumor development." (PMID 41184283, 2025). "Tumor‐adjacent normal tissue areas were not investigated in the present cohort; only wild‐type, EML4–ALK‐rearranged, KRAS‐mutated, and EGFR‐mutated LUAD samples were compared." (PMID 40621945, 2025). "This compound has shown selective inhibition on KRAS G12C protein, which exerts potent anti-tumour effects on both in vitro and in vivo models without any effects on WT KRAS protein." (PMID 39820726, 2025). "STK11 and KEAP1 mutations are also not reliable predictors of response to ICI therapy, given their association with a non-inflamed tumor microenvironment (TME) and frequent co-occurrence with mutations such as KRAS." (PMID 40535117, 2025). "LY3537982 has proved tolerance in patients who were previously intolerant to other KRAS G12C inhibitors and lacked high-grade liver toxicity when it was used in patients with multiple tumor types." (PMID 40597785, 2025). "Furthermore, we observed that an increase in KRAS WT CN correlates with a higher KRAS activity score, based on the MPAS signature both in cancer cell lines and in tumor samples from patients." (PMID 39711431, 2025). "However, recent research has highlighted that wt KRAS PDAC tumors still undergo significant genetic alterations that activate alternative signaling pathways and drive tumor progression." (PMID 40227826, 2025).
tumor (continued). "Moreover, low tumor mitotic activity was associated with better prognosis in LUAD subgroups with EGFR mutations or pan-negative (no oncogenic alteration in genes including KRAS, EGFR, BRAF, ERBB2, PIK3CA, ALK, and ROS1) but not in those with KRAS or BRAF mutations." (PMID 41404730, 2025). "The significant upregulation of KRAS signaling revealed that tumor cells in non-pCR have a greater degree of tumor malignancy." (PMID 40691458, 2025). "Designing TCRs that differentiate mutant from wild-type KRAS peptides and ensuring TCR-T cells target only tumor cells without causing toxicity are key issues." (PMID 40356763, 2025). "Contrary to the tumor-preventing effect of Tak1 ablation in KRAS-driven PDAC development, ablation of Rela did not prevent ADM and PDAC formation in KRASG12D mice (KRASG12D RelAΔAc), but instead, it even enhanced tumorigenesis." (PMID 39971907, 2025). "We analysed 142 samples from 39 KRAS wild‐type fully resected primary tumours of metastatic CRC patients undergoing anti‐EGFR therapy (in first‐, second‐ or third‐line treatment), covering the entire tumour, invasion front and six morphological regions." (PMID 40302146, 2025). "In our study, elevated PHLDA1 expression was associated with the activation of protumorigenic pathways such as EMT, KRAS, and TGF-β, suggesting that it may contribute to the regulation of tumor cell transformation, invasion, and migration." (PMID 40688078, 2025). "KRAS mutations, unlike EGFR and ALK, are associated with a history of smoking, high PD-L1 expression, and a high tumor mutational burden (TMB)." (PMID 40558308, 2025). "We propose that PHLDA1+ CAFs contribute to tumor growth and immune modulation by activating protumorigenic signaling pathways—such as PI3K/Akt, TGF-β, and KRAS—which, in turn, may impact patient prognosis and therapeutic response." (PMID 40688078, 2025). "Moreover, YAP serves as a critical transcriptional switch downstream of KRAS‐MAPK signaling, enhancing the expression of genes that promote neoplastic proliferation and tumor progression." (PMID 40895190, 2025). "Reducing LDs limits invasion in KRAS-mutant PDAC, which may help decrease immune suppression, tumor invasion, and drug resistance." (PMID 39859231, 2025). "Variations in ROS production between OVCA429 and OVCAR3 cells may be due to KRAS amplification in OVCAR3 cells, which can enhance ROS generation in tumor cells." (PMID 39625235, 2025). "Notably, SIAIS562055 monotherapy inhibited MIA PaCa-2/R tumor growth by 76.3% (P < 0.001) and demonstrated even greater antitumor efficacy, with a TGI of 100.5%, when combined with the KRAS inhibitor MRTX849." (PMID 39437162, 2025). "While KRAS, NRAS, and BRAF hot-spot mutations are very important drivers of tumorigenesis and tumor progression, it is important to note that they are not the only intrinsic features of colonic tissues dictating its consequences for tumorigenesis." (PMID 39857025, 2025). "Moreover, a low dose of warfarin below the anticoagulant dosage, effectively blocks γ‐carboxylation of the Gla domain of PRRG1, reverses its regulation on KRAS and EGFR, and PDAC in vivo tumour growth." (PMID 39843398, 2025). "SOS1 has a dominant role in GDP-GTP exchange and due to its unique participation in the negative feedback loop of the KRAS pathway, it has been recognized as a significant tumor target." (PMID 40244134, 2025). "Six of the nine vaccinated patients (67%) generated mutant KRAS specific T cell responses, and at median time of follow up of 25.3 months, five patients were without evidence of tumor recurrence." (PMID 40227779, 2025).